MAP4K4 (mitogen-activated protein kinase kinase kinase kinase 4)
Diseases named in the same sentence as MAP4K4 in open-access papers (continued):
Sharing a sentence is not in itself a finding about the gene and the disease.
brain tumor (5 papers, 2019 to 2025). "EndoA1 and A3 are highly expressed in SHH MB compared with other brain tumors and their expression correlates positively with MAP4K4 in this tumor type." (PMID 35296518, 2022). "The interaction of the STRIPAK complex with MAP4K4 confirms previous findings describing a direct interaction of STRIPAK with MST1/2, MST3/4, and MAP4Ks19,25,33,34 in a brain tumor, where MAP4K4 and STRN3/4 are highly expressed." (PMID 35941177, 2022). "Due to the essential role of MAP4K4 during neuro-pathophysiological processes, this molecule could be of particular relevance for targeting aberrant MAP4K4 functions in brain tumors as its metabolic stability and blood-brain barrier permeance was confirmed." (PMID 36568222, 2022). "Further in-depth investigations of the divergent molecular functions of MAP4K4 activity during onset and progression of brain tumors and neurodegeneration will be necessary to design disease-specific intervention strategies targeting differential MAP4K4 functions in these two disease entities." (PMID 36568222, 2022). "Future studies will focus on identifying the downstream molecular targets of MAP4K4 and determining whether MAP4K4 inhibition improves survival in orthotopic mouse brain tumor models in vivo." (PMID 31570734, 2019). "A recent genomic and proteomic analysis of a cohort of 218 pediatric brain tumors revealed increased levels of MAP4K4, EndoA1, and EndoA3—both at protein and RNA levels—but not of EndoA2, in primary MB and ganglioglioma tumor samples." (PMID 35296518, 2022).
ischemic stroke (5 papers, 2019 to 2023). A stroke disorder caused by obstruction of blood flow to the brain, due to thrombotic (local blood clot formation) or embolic (due to a blood clot or other material traveling from another site) event. "Silencing of lncRNA GAS5 suppressed neuron apoptosis in ischemic stroke through inhibiting DNMT3B-dependent methylation of MAP4K4." (PMID 35451738, 2022). "Interestingly, effectors of MAP4K4 have been proposed as therapeutic targets in cardiovascular disease and neuronal injury: at least in preclinical studies, inhibiting TAK1/MAP3K7 is protective in ischemic stroke." (PMID 30853557, 2019).
amyotrophic lateral sclerosis (4 papers, 2020 to 2024). Amyotrophic lateral sclerosis (ALS) is a neurodegenerative disease characterized by progressive muscular paralysis reflecting degeneration of motor neurons in the primary motor cortex, corticospinal tracts, brainstem and spinal cord. "Differentially expressed MAP4K4 in PD patients encodes a serine/threonine kinase whose activation has been shown to mediate motor neuron degeneration in amyotrophic lateral sclerosis." (PMID 39578713, 2024). "For example, thanks to iPSC-based screening, it was possible to identify a new application for ezogabine, an anti-epileptic drug, in amyotrophic lateral sclerosis (ALS) treatment and to highlight the beneficial effects of MAP4K4 gene silencing on an iPSCs-CMs model of ischemic injury." (PMID 32575374, 2020). "Unlike AD, where no functional studies using agents targeting MAP4K4 have been performed so far, MAP4K4 inhibition by the small molecule dual MAP4K4-GSK3 inhibitor kenpaullone was found to be motor-neuron protective in amyotrophic lateral sclerosis (ALS)." (PMID 36568222, 2022).
heart failure (4 papers, 2021 to 2025). Inability of the heart to pump blood at an adequate rate to meet tissue metabolic requirements. "Perhaps unsurprisingly, MAP4K4 activity is therefore linked to cardiovascular disease and heart failure, but it is also associated with other major diseases including cancer." (PMID 34032269, 2021). "MAP4K4 associates with striatins in cardiomyocytes and is linked to human heart failure, so could also be involved." (PMID 38718356, 2024). "MAP4K4 can activate c-Jun N-terminal kinases (JNKs), and studies in the heart suggest it links oxidative stress to JNKs and heart failure." (PMID 34032269, 2021).
infarction (3 papers, 2020 to 2025). A localised pathological necrosis of tissue resulting from obstruction of the blood supply usually by a thrombus, an embolus, or vascular torsion. "In contrast, MAP4K4 inhibition rescues mitochondrial function in cardiomyocytes, ameliorates apoptosis and reduces infarction size." (PMID 38724987, 2024). "This study is among the first to identify RBM25 as a regulator of ischemic HF through its modulation of MAP4K4 alternative splicing and downstream activation of the p38 MAPK signaling pathway using a post‐infarction rat model." (PMID 41409803, 2025). "Hearts injected with Map4k4-siRNA-loaded GeRPs (n = 3/group) or PBS (n = 5–6/group) were procured at 3 or 7 days after infarction; normal hearts without infarction or surgery served as reference controls (n = 8)." (PMID 33376632, 2020).
malignant melanoma (3 papers, 2019 to 2021). "Moreover, MAP4k4 belongs to the mammalian STE20/MAP4K family, which is often overexpressed in many types of human cancer and cancer cell lines, including malignant melanoma, because of its crucial role in transformation, invasiveness, adhesion, and cell migration." (PMID 31146393, 2019).
myocardial infarction (3 papers, 2019 to 2024). Gross necrosis of the myocardium, as a result of interruption of the blood supply to the area, as in coronary thrombosis. "MAP4K4 is activated in failing human hearts and induces oxidative stress to promote cell death in myocardial infarction models." (PMID 38724987, 2024).
thyroid cancer (3 papers, 2017 to 2023). "Putative target genes for miR-TG were identified using in silico tools, which pinpointed MAP4K4, an oncogene upregulated in thyroid cancer." (PMID 28855631, 2017).
autism spectrum disorder (2 papers, 2023). A spectrum of developmental disorders that includes autism, and Asperger syndrome. "First, MAP4K4 has a number of tissue-specific isoforms and is one of the autism spectrum disorders (ASD) genes after identifying de novo frameshift variants in neuron-specific exons and isoforms, which account for the reduced expression of MAP4K4 transcript." (PMID 37980537, 2023).
epidermoid carcinoma (2 papers, 2023 to 2025). "In the first step, we measured YAP, LATS1/2, JNK1/2, ABL1 and MAP4K4 gene expression in the A431 cell line to identify which disturbances in the Hippo pathway and their regulators are present in the standardized squamous cell carcinoma cell line." (PMID 40149574, 2025). "In this work, we used the epidermoid carcinoma cell line A431 as a model to study the role of the kinase MAP4K4 in regulating the collective migration of cancer cell clusters in vitro." (PMID 37369604, 2023).
epilepsy (2 papers, 2023 to 2024). A brain disorder characterized by episodes of abnormally increased neuronal discharge resulting in transient episodes of sensory or motor neurological dysfunction, or psychic dysfunction. "Previous reports highlighted MAP4K4 as a crucial player in neuronal pathways in vitro and found MAP4K4 mutated in a cohort of patients with Neurodevelopmental disorders and epilepsy." (PMID 36469137, 2023).
Hyperinsulinemia (2 papers, 2016 to 2020). An increased concentration of insulin in the blood. "Here, we demonstrate that inducible, systemic loss of Map4k4 ameliorates long-term HFD-induced hyperinsulinemia." (PMID 27226575, 2016). "Insulin itself can create a positive feedback loop by activating ATF2 in this pathway solely or mediated by MAPK8 (preceded by MAP4K4) or PRKCE which can eventually lead to hyperinsulinemia." (PMID 32993798, 2020). "In summary, we have demonstrated that Map4k4 is required for chronic HFD-induced hyperinsulinemia in mice." (PMID 27226575, 2016). "Thus, Map4k4 mediates hyperinsulinemia in chronic obesity by promoting islet hypertrophy and insulin secretion from pancreatic β cells." (PMID 27226575, 2016). "Taken together, these data suggest that Map4k4 is not required to mediate hyperinsulinemia in response to acute stress but is required for maintaining insulin levels in long term HFD stress." (PMID 27226575, 2016).
liver cancer (2 papers, 2019 to 2021). An epithelial or non-epithelial malignant neoplasm that arises from the liver. "However, in contrast to other cancer types, so far only three studies have identified and experimentally proved target genes of miR-622 in liver cancer (i.e., mitogen-activated protein 4 kinase 4 (MAP4K4), CXC chemokine receptor 4 (CXCR4), and kirsten rat sarcoma (KRAS)." (PMID 33803354, 2021).
neuroblastoma (2 papers, 2018 to 2022). Neuroblastoma (NB) is the most common solid, extracranial childhood tumor. "Although there are few reports on the involvement of Map4k4 in neuropathic pain, it can affect the growth of neuronal axons and dendrites in the SH-SY5Y cell line derived from human neuroblastoma." (PMID 36045396, 2022).
abdominal aortic aneurysm (1 paper, 2022). Enlargement and ballooning of the vessel that supplies arterial blood to the abdomen, pelvis and legs. "RhoA is required in vascular smooth muscle cells to inhibit MAP4K4 and prevent abdominal aortic aneurysm formation." (PMID 36207400, 2022).
Alzheimer disease (1 paper, 2022). A progressive, neurodegenerative disease characterized by loss of function and death of nerve cells in several areas of the brain leading to loss of cognitive function such as memory and language. "Single-cell mRNA expression analysis of pre-frontal cortex tissue of Alzheimer’s disease (AD) patients identified increased MAP4K4 expression as a potential biomarker of the disease." (PMID 36568222, 2022).
aortic atherosclerosis (1 paper, 2024). A atherosclerosis that involves the aorta. "EC-specific MAP4K4 deletion alleviates aortic atherosclerosis by decreasing macrophage permeation and lipid accumulation." (PMID 38724987, 2024).
Azoospermia (1 paper, 2022). Absence of any measurable level of sperm,whereby spermatozoa cannot be observed even after centrifugation of the semen pellet. "Notably, MAP4K4 protein was lower in the testes of patients with non-obstructive azoospermia than those with normal spermatogenesis as shown by Western blots and immunohistochemistry." (PMID 36497065, 2022).
Cachexia (1 paper, 2023). Severe weight loss, wasting of muscle, loss of appetite, and general debility related to a chronic disease. "These preclinical findings suggest that MAP4K4 might be a viable target for cancer-associated cachexia." (PMID 37190200, 2023). "In the present review, we discuss the functional role of MAP4K4 in malignant/non-malignant diseases and cancer-associated cachexia and its possible use in targeted therapy." (PMID 37190200, 2023).
cardiac hypertrophy (1 paper, 2025). "Recent studies have demonstrated that miR-30d prevents pathological cardiac hypertrophy via negatively regulating its target genes MAP4K4 and GRP78 and inhibiting the prohypertrophic nuclear factor of activated T cells." (PMID 39943804, 2025).
cardiomyopathy (1 paper, 2020). A disease of the heart muscle or myocardium proper. "On the basis of these highly encouraging findings, we postulate MAP4K4 to be a well-posed target toward suppressing human cardiac cell death and dysfunction in drug-induced cardiomyopathies due to DOX and, perhaps, other chemotherapeutic agents." (PMID 32694738, 2020). "Here, based upon the activation of endogenous MAP4K4 in DOX-induced cardiomyopathy and in cardiomyocytes treated acutely with DOX, we prove that DOX toxicity in two independent lines of hPSC-CMs is suppressed by two small-molecule inhibitors of MAP4K4." (PMID 32694738, 2020). "A further role for MAP4K4 was proposed in heart muscle cell death triggered by cardiotoxic anti-cancer drugs, given its reported activation in failing human hearts with doxorubicin (DOX) cardiomyopathy, and its activation acutely by DOX in cultured cardiomyocytes." (PMID 32694738, 2020).
chronic heart failure (1 paper, 2019). "Activation of human cardiac MAP4K4 was prevalent in chronic heart failure from diverse etiologies, associated with active (cleaved) caspase-3, a mediator of apoptosis, and activation of the MAP3K intermediary, TAK1, which itself can drive cardiac cell death." (PMID 30853557, 2019).
Chylothorax (1 paper, 2022). The presence of chyle in the thoracic cavity. "Conditional KO of Map4k4 in endothelial cells of mice resulted in no surviving homozygous animals and chylothorax, indicating an essential role of MAP4K4 in developing endothelia of blood and lymphatic vasculature." (PMID 36568222, 2022).
COVID-19 (1 paper, 2021). A disease caused by infection with severe acute respiratory syndrome coronavirus 2. "In addition, CD14 and MAP4K4 were highly enriched in hydroxymethylation for patients with COVID-19 (p = 0.00033 and 0.044), and the levels of hydroxymethylation increased gradually in groups moderate, severe, and critical patients and MI." (PMID 35071229, 2021).
endothelial dysfunction (1 paper, 2024). In vascular diseases, endothelial dysfunction is a systemic pathological state of the endothelium (the inner lining of blood vessels) and can be broadly defined as an imbalance between vasodilating and vasoconstricting substances produced by (or acting on) the endothelium. "In conclusion, our findings demonstrate that MAP4K4 plays an important role in endothelial dysfunction in DCM and reveal that SNO-Drp1 and ferroptosis activation may act as downstream targets, representing potential therapeutic targets for DCM." (PMID 38724987, 2024). "Since endothelial dysfunction is closely correlated with mitochondrial functional and structural damage during HG/FFA injury, we explored the effects of silencing MAP4K4 on mitochondrial function." (PMID 38724987, 2024).
Hepatic steatosis (1 paper, 2022). Steatosis is a term used to denote lipid accumulation within hepatocytes. "We detected a significant correlation between MAP4K4 transcript abundance and the severity of the components of NAS (liver steatosis, inflammation, hepatocellular ballooning) as well as composite NAS." (PMID 35679904, 2022). "We found that MAP4K4 mRNA expression in human liver biopsies was positively correlated with key hallmarks of NAFLD (i.e., liver steatosis, lobular inflammation, hepatocellular ballooning, and fibrosis)." (PMID 35679904, 2022). "Furthermore, we found that MAP4K4 levels in human liver biopsies were positively correlated with the key lesions of NAFLD/NASH (i.e., hepatic steatosis, inflammation, fibrosis, and hepatocellular ballooning)." (PMID 35679904, 2022).
Infertility (1 paper, 2022). "It has been suggested that MAP4K4 affects SH3PXD2A-binding enzymes ADAM12, ADAM15, and ADAM19, which has been shown to be associated with infertility in mutant mouse models." (PMID 36497065, 2022).
Intellectual disability (1 paper, 2023). "Moreover, a chromosomal deletion of a locus including, among other genes, MAP4K4, was reported in a patient with intellectual disability." (PMID 36469137, 2023).
laryngeal carcinoma (1 paper, 2025). Carcinoma that arises from the laryngeal epithelium. "Additionally, studies have demonstrated that SOX2 contributes to the progression of laryngeal cancer, where it exerts crucial regulatory effects on apoptosis and metastasis of laryngeal cancer cells through the MAP4K4/JNK signaling pathway." (PMID 39976818, 2025).
liver disease (1 paper, 2024). "The results shed new light on the role of MST3, STK25, and MST4, as well as their interactions with PDCD10, MAP4K4, and HSD17B11, in the control of liver lipid homeostasis and metabolic dysfunction–associated steatotic liver disease susceptibility." (PMID 39395791, 2024).
liver fibrosis (1 paper, 2022). "Furthermore, the histological score of liver fibrosis was positively correlated with the hepatic MAP4K4 expression." (PMID 35679904, 2022).
lumbar disc herniation (1 paper, 2023). "miR-547-3p regulates inflammatory cytokines by targeting MAP4K4, alleviating neuropathic pain from lumbar disc herniation." (PMID 38187091, 2023).
lymph node metastasis (1 paper, 2019). "It was reported that the expression levels of MAP4K4 in CRC patients with lymph node metastasis were higher than that in patients without metastasis." (PMID 30710069, 2019).
male infertility (1 paper, 2022). The inability of the male to effect fertilization of an ovum after a specified period of unprotected intercourse. "Considered together, our data implicate that MAP4K4/JNK signaling pathway mediates proliferation and apoptosis of human SSCs, which provides a novel insight into molecular mechanisms governing human spermatogenesis and might offer new targets for gene therapy of male infertility." (PMID 36497065, 2022).
mastitis (1 paper, 2021). Inflammation of breast tissue during lactation or postpartum due to an obstructed duct or infection. "MAP4K4 gene has been reported to be associated with milk yield, protein percentage, and mastitis susceptibility in Chinese Holstein cattle." (PMID 33806889, 2021).
metastatic cancers (1 paper, 2018). A carcinoma which has spread from the original site of growth to another anatomic site. "Molecular targeting of the underlying accelerated endocytosis and receptor recycling could represent a novel approach to block pro-migratory effector functions of MAP4K4 in metastatic cancers." (PMID 29796184, 2018).
metastatic disease (1 paper, 2018). "The parallel increase of c-Met and MAP4K4 expression in SHH MB could predict an increased potential of these tumors to infiltrate brain tissue and cause metastatic disease." (PMID 29796184, 2018).
neuro-degenerative diseases (1 paper, 2022). "Studies explored the relationship between MAP4K4 and neuro-degenerative diseases." (PMID 35615282, 2022).
neutropenia (1 paper, 2025). A decrease in the number of neutrophils found in the blood. "The loss of MAP4K4 in hematopoietic stem cells and progenitors in mice induced neutropenia and impeded the differentiation of neutrophils in the bone marrow." (PMID 40096134, 2025). "We found that the loss of MAP4K4 expression in HSPCs leads to neutropenia in mice and MAP4K4 regulates cell apoptosis during neutrophil differentiation." (PMID 40096134, 2025). "Loss of MAP4K4 expression in HSPCs results in neutropenia, and MAP4K4 regulates cell apoptosis during neutrophil differentiation in bone marrow." (PMID 40096134, 2025).
osteosarcoma (1 paper, 2021). A usually aggressive malignant bone-forming mesenchymal neoplasm, predominantly affecting adolescents and young adults. "The HGK (MAP4K4 or mitogen activated protein kinase kinase)-SAPK/JNK-Jun signal axis can be recruited to the SESN2 promoter to activate SESN2/AMPK-α and induce Tan IIA -mediated autophagy and osteosarcoma growth inhibition." (PMID 34819867, 2021).
ovarian tumors (1 paper, 2023). "Transcriptomic sequencing of paired primary ovarian tumors and metastases unveiled that MAP4K4, a serine/threonine kinase belongs to the Ste20 family of kinases, was highly expressed in metastatic sites." (PMID 36922678, 2023).
pancreatic adenocarcinoma (1 paper, 2023). "Compared to the pancreatic adenocarcinoma cells, AsPC-1, the pancreatic epithelial cells, Panc-1, expressed a higher level of MAP4K4 expression." (PMID 36683274, 2023).
papillary thyroid cancer (1 paper, 2023). "For instance, MAP4K4 mRNA was reported to be alternatively spliced in papillary thyroid cancer samples by RBM17, which causes phosphorylation of downstream signaling pathways." (PMID 36977901, 2023).
Parkinson disease (1 paper, 2025). A progressive degenerative disorder of the central nervous system characterized by loss of dopamine producing neurons in the substantia nigra and the presence of Lewy bodies in the substantia nigra and locus coeruleus. "MAP4K4 was recently suggested to be a risk gene and a potential biomarker for Parkinson’s disease." (PMID 41282267, 2025).
premature ovarian failure (1 paper, 2024). "Another target gene, MAP4K4, of MSTRG.2494, has been linked to the development of premature ovarian failure due to gene rearrangement." (PMID 38383305, 2024).